FXR1 (FMR1 autosomal homolog 1)
Diseases named in the same sentence as FXR1 in open-access papers (continued):
Sharing a sentence is not in itself a finding about the gene and the disease.
ovarian carcinoma (6 papers, 2020 to 2026). A malignant neoplasm originating from the surface ovarian epithelium. "RNA interference (RNAi) of FXR1 using a locked nucleic acid (LNA) form of siRNA (siFXR1-LNA) inhibits tumor growth, ascites formation, and metastasis of ovarian cancer more efficiently than the native form of FXR1 siRNA in vivo." (PMID 41932914, 2026). "Overexpression of cMYC by FXR1 increased cell-cycle regulators such as cyclin E1, D1, and CDKs, promoting the growth of ovarian cancer." (PMID 38238286, 2024). "FXR1 promotes the translation of the cMYC oncoproteins by binding to the AREs within cMYC mRNA, which is essential for ovarian cancer progression and aggressiveness." (PMID 38238286, 2024). "In ovarian cancer cells, transient and constitutive FXR1 inhibition by shRNA and siRNA reduced cell proliferation, colony formation, migratory, and invasion ability and suppressed tumor development in vivo." (PMID 38238286, 2024). "shRNA and siRNA were used to inhibit FXR1 in mice ovarian cancer cells." (PMID 38238286, 2024). "Fxr1 is RNA-binding protein, which promotes cancer cell proliferation, including prostate cancer cells and ovarian cancer cells, whereas male mouse heart ILC2s showed upregulation of α-linolenic acid metabolism, which decreases T-cell proliferation and differentiation." (PMID 36316644, 2022). "FXR1 siRNAs in nanoliposomes composed of 1,2-Dioleoyl-sn-glycero-3-phosphocholine (DOPC) reduced ovarian cancer growth and metastasis." (PMID 38238286, 2024). "FXR1 and IGF2BP2 were thus suggested as direct targets of niclosamide with a critical role in driving multiple oncogenic pathways in ovarian carcinoma." (PMID 37259418, 2023). "Quite recently, 2 RNA-binding proteins (RBPs)—FXR1 and IGF2BP2—were identified as key signal transduction mechanisms altered by niclosamide in ovarian cancer." (PMID 37259418, 2023).
glioma (5 papers, 2018 to 2022). A benign or malignant brain and spinal cord tumor that arises from glial cells (astrocytes, oligodendrocytes, ependymal cells). "However, far less is known about the role of FXR1-mediated regulation of gene expression in glioma as well as the underlying mechanism." (PMID 30691465, 2019). "In order to further study the molecular mechanism of FXR1 in glioma cells via stabilizing MIR17HG, we studied the interaction between MIR17HG and downstream miRNAs." (PMID 30691465, 2019). "we investigated the expression of FXR1, MIR17HG, miR-346, miR-425-5p, TAL1 and DEC1 in glioma cells and elucidated the underlying molecular mechanisms in glioma cells." (PMID 30691465, 2019). "Herein, the expression and function of RNA binding proteins FXR1 were investigated in human glioma cells." (PMID 30691465, 2019). "Using lncRNAs microarray, we found MIR17HG was significantly downregulated in glioma cells treated with sh-FXR1." (PMID 30691465, 2019). "Flow cytometry analysis demonstrated that silence of FXR1 remarkedly increased apoptosis of glioma cells." (PMID 30691465, 2019). "In the present study, we found that FXR1 exhibited high expression levels in glioma tissues and cells." (PMID 30691465, 2019). "Inhibition of FXR1 hindered malignant biological behaviors of glioma cells via destabilizing MIR17HG." (PMID 30691465, 2019). "The missing events were a high-level episomal MYCN amplification in retinoblastoma SJRB051 and an FXR1–BRAF fusion in low-grade glioma SJLGG026." (PMID 30262806, 2018). "Downregulation of FXR1 can result in the inhibition of glioma cell progression." (PMID 36498797, 2022). "Moreover, FXR1 regulates the biological behavior of glioma cells by increasing thestability of MIR17HG." (PMID 32104542, 2020). "Inhibition of FXR1 hindered malignant biological behaviors of glioma cells." (PMID 30691465, 2019). "In addition, inhibition of FXR1 combined with inhibition of MIR17HG significantly impeded glioma cell growth." (PMID 30691465, 2019). "Downregulation of FXR1 or MIR17HG resulted in inhibition of glioma cells progression." (PMID 30691465, 2019). "Also, knockdown of MIR17HG increased suppression of glioma cell progression induced by inhibition of FXR1." (PMID 30691465, 2019). "FXR1/MIR17HG/miR-346(miR-425-5p)/TAL1/DEC1 axis plays a novel role in regulating the malignant behavior of glioma cells, which may be a new potential therapeutic strategy for glioma therapy." (PMID 30691465, 2019). "We also found that FXR1 regulates the biological behavior of glioma cells via stabilizing MIR17HG." (PMID 30691465, 2019). "Moreover, the glioma cells treated with sh-FXR1 and sh-MIR17HG exhibited weaker proliferation, migration and invasion abilities, and higher apoptosis ratio." (PMID 30691465, 2019). "The expression of FXR1 in glioma tissues and cells were detected by western blot." (PMID 30691465, 2019). "FXR1 expression was significantly increased in glioma tissues of different grades compared with normal brain tissues (NBTs), and the expression was positively correlated with the pathological grade of glioma tissues." (PMID 30691465, 2019). "Therefore, we predicted that MIR17HG was involved in FXR1-mediated regulation on glioma cells." (PMID 30691465, 2019). "Cell Counting Kit-8, transwell assays, and flow cytometry were used to investigate the function of FXR1 and MIR17HG in malignant biological behaviors of glioma cells." (PMID 30691465, 2019). "In the present study, we found that expression of FXR1 and MIR17HG were elevated in glioma tissues and cells." (PMID 30691465, 2019). "Stable knockdown of FXR1 and MIR17HG in glioma cells were established to explore the function of FXR1, MIR17HG in glioma cells." (PMID 30691465, 2019). "In the present study, we profiled the expressions of FXR1, MIR17HG, miR-346, miR-425-5p and TAL1 in glioma tissues and cells." (PMID 30691465, 2019). "Western blot were used to explore the expression of FXR1, TAL1 and DEC1 in glioma tissues and cells." (PMID 30691465, 2019).
glioma (continued). "Compared with sh-FXR1-NC + sh-MIR17HG-NC group, the proliferation, migration and invasion abilities of U87 and U251 cells were decreased in thesh-FXR1 + sh-MIR17HG-NC, sh-FXR1-NC + sh-MIR17HG and sh-FXR1 + sh-MIR17HG groups, and the apoptosis of glioma cells were significantly increased." (PMID 30691465, 2019). "Bioinformatics software (Starbase) reveals that FXR1 harbor a putative binding site of MIR17HG, which suggested FXR1 may play a role via increasing the stability of MIR17HG in glioma." (PMID 30691465, 2019). "Moreover, compared with inhibition of FXR1 or MIR17HG alone, the inhibition of FXR1 and inhibition of MIR17HG significantly increased the expression of miR-346 and miR-425-5p, further enhanced the suppression of glioma cell malignant progression." (PMID 30691465, 2019).
mental retardation (5 papers, 2013 to 2023). "For example, human orthologs to fly genes CASK (CASK), Mnb (DYRK1A), Dlg-1 (DLG1), Cdc42 (CDC42), Fmr1 (FMR1, FXR1/2), trio (TRIO), Nedd4 (NEDD4L/NEDD4) and CamKII (CAMK2A/B/D) have been linked to intellectual disability." (PMID 37759179, 2023). "FXR1 on the other hand is an RNA-binding protein and ortholog of the fragile X and mental retardation gene FMR1." (PMID 35666183, 2022). "Fxr1 is a RNA-binding protein and is an autosomal paralogue of fmrp (fragil X mental retardation 1), important for normal female reproductive function and cognition development in humans." (PMID 26581195, 2015).
bipolar disorder (4 papers, 2016 to 2025). A disorder of the brain that causes unusual shifts in mood, energy, activity levels and the ability to carry out day-to-day tasks. "Several biological functions that are relevant to the effects of lithium in bipolar disorder can potentially be affected by FXR1." (PMID 36504683, 2022). "Interaction between polymorphisms affecting cortical expression of the FXR1 and GSK3B genes have been shown to regulate mood-related behavioral dimensions in healthy humans and patients with bipolar disorder." (PMID 29706865, 2018). "For example, FXR1 has been shown to affect mitochondrial functions, oxidative stress, neurogenesis, and cell proliferation, which can be pertinent to phenotypes observed in studies of people with bipolar disorder and patient derived systems." (PMID 36504683, 2022).
colorectal cancer (4 papers, 2021 to 2026). A primary or metastatic malignant neoplasm that affects the colon or rectum. "FXR1 (FMR1 autosomal homolog 1) has previously been implicated in cancers such as hepatocellular carcinoma, colorectal cancer, and urothelial carcinoma." (PMID 39480826, 2024).
hepatocellular carcinoma (4 papers, 2023 to 2026). A malignant tumor that arises from hepatocytes. "In a loss of function study, FXR1 knockdown reduces hepatocellular carcinoma (HCC) cell invasion and migration via TGF-β modulation, whereas upregulation in HCC cells increases cell invasion which is abrogated by inhibiting SMAD2/3." (PMID 38238286, 2024). "FXR1 can promote the proliferation, invasion, and migration of hepatocellular carcinoma, and its action is mediated by Smad2/3." (PMID 37517087, 2023).
lung adenocarcinoma (4 papers, 2014 to 2024). A carcinoma that arises from the lung and is characterized by the presence of malignant glandular epithelial cells. "We then confirmed this kinetic effect on the endogenous FXR1 mRNA, which was shown to be alternatively spliced in the presence of U2AF1-S34F in both AML and lung adenocarcinoma." (PMID 25271374, 2014). "In addition, we tested the mRNA level changes of PRMT5 and FXR1 in The Cancer Genome Atlas (TCGA) HNSCC and lung adenocarcinoma data sets." (PMID 38709899, 2024). "Hence, targeting PRMT5 to modulate FXR1 functions is significant and may provide a unique anti-tumor response for HNSCC and lung adenocarcinoma patients." (PMID 38709899, 2024).
melanoma (4 papers, 2017 to 2022). A malignant, usually aggressive tumor composed of atypical, neoplastic melanocytes. "Moreover, melanoma cells with Fbxo4I377M mutation also exhibit increased Fxr1 levels, consistent with Fbxo4-dependent regulation of Fxr1 in normal cells, and the disruption of this pathway in human cancers." (PMID 29142209, 2017). "Evaluation of Fxr1 expression data deposited in TCGA and GTEx databases highlights a significant increase of Fxr1 in melanoma patients." (PMID 36329064, 2022). "Thirty-two (32/32) melanomas immunolabelled for LTA4H and 33/34 for FXR1." (PMID 34966807, 2021).
non-small cell lung carcinoma (4 papers, 2019 to 2023). A group of at least three distinct histological types of lung cancer, including non-small cell squamous cell carcinoma, adenocarcinoma, and large cell carcinoma. "In non-small cell lung cancer, FXR1 is overexpressed in the tissues and cells, silencing of FXR1 exhibited reduced cell growth and elevated cell apoptosis ratio via destabilizing ECT2 mRNA." (PMID 30691465, 2019).
Anxiety (3 papers, 2018 to 2020). Intense feelings of nervousness, tension, or panic often arise in response to interpersonal stresses. "The modulation of neuronal activity by Gsk3β and Fxr1 in the mPFC is most probably linked to their effects on anxiety-related behaviors." (PMID 29706865, 2018). "Mice with reduced Gsk3β or elevated Fxr1 expression in mPFC showed decreased anxiety-related behaviors and reduced AMPA mediated excitatory postsynaptic currents." (PMID 29706865, 2018). "This indicates that either selective increase in the expression of Fxr1 or knockout of Gsk3b in mPFC neurons is sufficient to reduce anxiety." (PMID 29706865, 2018). "In contrast to gene inactivation, Fxr1 AAV-mediated overexpression in mPFC neurons of adult mice affects anxiety-related behaviors." (PMID 30087606, 2018). "In line with this, animal studies demonstrated that Gsk3β can directly regulate Fxr1 levels in response to mood stabilizers and that increase in Fxr1 expression results in a decrease in anxiety-related behaviors." (PMID 30087606, 2018). "Thus, we evaluated anxiety-related behavioral outcomes after augmentation of Fxr1 and reduction of Gsk3β levels." (PMID 29706865, 2018).
atherosclerosis (3 papers, 2020 to 2024). A disease characterized by the build-up of fatty material and calcium deposition in the arterial wall resulting in partial or complete occlusion of the arterial lumen. "A recent observation indicated lncRNA TUG1 regulates ApoM to promote atherosclerosis progression through miR-92a/FXR1 axis." (PMID 34057025, 2021).
colon carcinoma (3 papers, 2021 to 2022). "Similar to HeLa cells, about 20% of non-transformed RPE-1 and chromosomally stable diploid DLD-1 colon carcinoma cells showed the presence of CNGs, which was strongly increased upon the deletion of FXR1." (PMID 34977012, 2021).
esophageal cancer (3 papers, 2022 to 2024). A primary or metastatic malignant neoplasm involving the esophagus. "Further studies have shown that RNA m6A can negatively regulate the DNA methylation of esophageal cancer through FMR1 Autosomal Homolog 1 (FXR1) and TET1 and play an important role in the development of cancer." (PMID 36750826, 2023). "We have recently identified that FXR1 overexpression destabilizes PDZK1IP1 and ATOH8 mRNA expression and promotes the development of esophageal cancer." (PMID 38238286, 2024).
liver cancer (3 papers, 2022 to 2023). An epithelial or non-epithelial malignant neoplasm that arises from the liver. "RT-qPCR showed that TFDP1, NDRG1, and FXR1 were expressed at higher levels in different liver cancer cell lines compared to normal liver cells." (PMID 37517087, 2023). "We used the GSE39791 dataset for validation and could see that the expression of TFDP1, NDRG1 and FXR1 in liver cancer tissues was significantly higher than that in normal tissues." (PMID 37517087, 2023). "Finally, IHC results showed that the expression of FXR1 and NDRG1 was significantly higher in liver cancer tissues than in normal tissues." (PMID 37517087, 2023).
neuroblastoma (3 papers, 2019 to 2023). Neuroblastoma (NB) is the most common solid, extracranial childhood tumor. "We observed that the green fluorescence protein (GFP), examined as a reporter, was reduced in Neuro2a (N2a) cell, a mouse neuroblastoma cell line, where Dlg4 and Fxr1 were knocked down." (PMID 36732356, 2023). "At the next step, the cells were stained with Thioflavin S. FXR1 forms both diffuse and granular structures around the nucleus of neuroblastoma cells." (PMID 31831836, 2019). "We tested the ability of the FXR1 protein to form amyloid aggregates in a human neuroblastoma cell culture." (PMID 31831836, 2019).
prostate carcinoma (3 papers, 2020 to 2022). A carcinoma that arises from epithelial cells of the prostate gland. "In prostate cancer cells, FXR1 negatively regulated FBXO4 transcripts via direct association with its 3’UTR and promoted mRNA degradation." (PMID 36498797, 2022). "RASSF2, which is a tumor-suppressor in the prostate cancer mouse model, might be coregulated by FXR1, FXR2, HNRNPA1, PTBP1, G3BP1, HNRNPF, and SRSF7." (PMID 32316190, 2020).
uveal melanoma (3 papers, 2020 to 2024). A melanoma derived from melanocytes of the uveal tract. "Among them, an increased expression in Leukotriene A4 hydrolase (LTA4H) and Fragile X mental retardation-related protein 1 (FXR1) genes were related to metastasizing behavior in both human and canine uveal melanoma." (PMID 34966807, 2021). "LTA4H and FXR1 have been previously found to be over-expressed in both human and canine uveal melanomas and LTA4H has also been reported to be upregulated in feline ocular melanomas." (PMID 34966807, 2021). "Interestingly, expression profiling using a 12‐gene assay reliably distinguished metastasising from non‐metastasising uveal melanomas in humans and four of these genes (HTR2B, FXR1, LTA4H, and CDH1) are overexpressed in metastasising canine uveal melanoma." (PMID 32652526, 2020).
breast tumors (2 papers, 2017 to 2021). "Therefore, we postulate that FXR1 is a novel prognostic biomarker specific for lung metastasis in TNBC and further validated the association of FXR1 protein with distant metastasis in TNBC using IHC on 69 breast tumors." (PMID 28387221, 2017). "FXR1 was most significantly associated with lung metastasis only in TNBC, therefore we elected to validate this finding using immunohistochemistry on 69 breast tumors." (PMID 28387221, 2017).
facioscapulohumeral muscular dystrophy (2 papers, 2016 to 2020). An autosomal dominant disorder affecting the skeletal muscles of the face, scapula, and upper arm. "In addition to its amplification in lung, breast, and ovarian as well as head and neck cancers, FXR1 was shown to be down-regulated in other human pathologies such as facioscapulohumeral muscular dystrophy, an inherited myopathy." (PMID 27812105, 2016).
respiratory failure (2 papers, 2018 to 2022). The significant impairment of gas exchange within the lungs resulting in hypoxia, hypercarbia, or both, to the extent that organ tissue perfusion is severely compromised. "Homozygous FXR1 knockout neonates died shortly after birth, most likely due to cardiac or respiratory failure." (PMID 34291416, 2022). "Fxr1 KO mice die shortly after birth from cardiac and respiratory failure, thus behavioral testing is only possible after brain-specific alterations of Fxr1 expression." (PMID 30087606, 2018).
retinoblastoma (2 papers, 2018 to 2024). A malignant tumor that originates in the nuclear layer of the retina. "The gene ontologies for list 6- linked CHTOP, FXR1, and REST to Retinoblastoma." (PMID 39480826, 2024). "We propose that CHTOP, FXR1, and REST are novel genes in Retinoblastoma." (PMID 39480826, 2024).
squamous cell carcinoma (2 papers, 2019 to 2023). A carcinoma arising from squamous epithelial cells. "Moreover, FXR1 expression is upregulated in the squamous cell carcinoma of the head and neck." (PMID 30691465, 2019).
autistic spectrum disorder (1 paper, 2024). "For instance, MAP1B, a microtubule filament protein, the prominent target of FXR1, is also targeted by FMRP and is associated with autistic spectrum disorder and autophagy." (PMID 38709899, 2024).
bladder cancer (1 paper, 2022). "To further characterize the pathological role of FXR1, we generated a patient-derived organoid line of bladder cancer in three-dimensional culture to recapitulate the pathological and genomic features of human bladder cancer." (PMID 35194031, 2022).
cardiac arrest (1 paper, 2015). Cessation of breathing and/or cardiac function. "It was previously shown that loss of Fragile X protein, FXR1 leads to perinatal lethality in mice possibly due to sudden cardiac arrest, whereas its reduction in zebrafish leads to a reduction in cardiac function." (PMID 26571124, 2015).
Fanconi anemia (1 paper, 2022). Fanconi anemia (FA) is a hereditary DNA repair disorder characterized by progressive pancytopenia with bone marrow failure, variable congenital malformations and predisposition to develop hematological or solid tumors. "Additionally, FXR1 can physically interact with MRE11, which our group has previously identified as important for R-loop suppression by the Fanconi Anemia pathway." (PMID 35666183, 2022).
Hypertension (1 paper, 2020). The presence of chronic increased pressure in the systemic arterial system. "PPAT and FXR1 are pivotal molecules in the control of blood pressure circadian rhythm by the kidney in hypertension." (PMID 33463674, 2020).
infantile epilepsy (1 paper, 2025). "At the protein level, western blots validated expression changes in CBS (mental retardation), NEAS/SPTAN1 (associated with infantile epilepsy), FBLN1 (cardiac morphogenesis), FXR1 (muscle development), and SHANK2 (neuronal differentiation in the retina)." (PMID 39508990, 2025).